CXCL5 (C-X-C motif chemokine ligand 5)
Diseases named in the same sentence as CXCL5 in open-access papers (continued):
Sharing a sentence is not in itself a finding about the gene and the disease.
squamous cell carcinoma (5 papers, 2018 to 2023). A carcinoma arising from squamous epithelial cells. "In a subsequent study, the master transcription factor SOX2, a lineage-specific oncogene for squamous cell carcinomas, was found to be overexpressed and to promote tumor associated neutrophil (TANs)-accumulation by upregulating CXCL5 (the mouse homolog of human CXCL6) expression." (PMID 33953163, 2021). "CXCL5 directly induces cancer cell proliferation and invasion and has been reported to be over-expressed in several cancer forms, including squamous cell cancer." (PMID 37745296, 2023).
abdominal aortic aneurysm (4 papers, 2012 to 2023). Enlargement and ballooning of the vessel that supplies arterial blood to the abdomen, pelvis and legs. "In contrast, the inhibition of RAC1 can significantly inhibit the activation of NF-κB and lead to decreased expression of MMP-9, MCP-2 and CXCL5 in abdominal aortic aneurysm tissue." (PMID 36835806, 2023). "Recent studies have shown that CXCL5 is up-regulated in abdominal aortic aneurysms (AAA), making it a candidate for potential future anti-inflammatory therapy strategies in MFS." (PMID 29530068, 2018). "CXCL5 has also been reported to be up-regulated in abdominal aortic aneurysm (AAA)." (PMID 29530068, 2018).
acute coronary syndrome (4 papers, 2012 to 2026). Signs and symptoms related to acute ischemia of the myocardium secondary to coronary artery disease. "We measured CXCL5 levels in platelet-poor plasma in 826 consecutive patients included in the "Risk Markers in the Acute Coronary Syndrome" (RACS) study (ClinicalTrials.gov Identifier: NCT00521976)." (PMID 41898605, 2026). "We then went on to show an association between the CXCL5 -156 G > C polymorphism and worse outcomes in patients with acute coronary syndromes." (PMID 23245743, 2012). "However, polymorphisms in CXCL5 gene are correlated with acute coronary syndrome, a disease where more numerous plaque-destabilizing neutrophils have been observed in lesions of men compared to women." (PMID 26617980, 2015). "Previous studies on CXCL5 in atherogenesis are to some degree conflicting, with scarce outcome data following acute coronary syndrome." (PMID 41898605, 2026). "We have shown CXCL5 polymorphisms to be associated with ENA-78 concentrations, blood pressure, and prognosis following acute coronary syndromes." (PMID 23245743, 2012).
acute respiratory distress syndrome (4 papers, 2019 to 2025). Progressive and life-threatening pulmonary distress in the absence of an underlying pulmonary condition, usually following major trauma or surgery. "PLCε-mediated augmentation of the production of the CXC family of chemokines, in particular Cxcl5, in AECs plays a crucial role in neutrophilic alveolar inflammation accompanying ALI, suggesting that PLCε may be a potential molecular target for the treatment of acute respiratory distress syndrome." (PMID 30634975, 2019).
Cirrhosis (4 papers, 2019 to 2023). A chronic disorder of the liver in which liver tissue becomes scarred and is partially replaced by regenerative nodules and fibrotic tissue resulting in loss of liver function. "Importantly, our study identified CXCL5, CXCL9, and CXCL10 as universal HCC markers, independent from underlying etiology of cirrhosis." (PMID 36982370, 2023).
cutaneous melanoma (4 papers, 2019 to 2023). A primary melanoma arising from atypical melanocytes in the skin. "Forsthuber A and others found that CXCL5 played a role as a regulator of neutrophil function in cutaneous melanoma." (PMID 33585219, 2020). "This study analyzed baseline serum levels of CXCL5, CXCL10, and CCL22 in 46 cases of advanced cutaneous melanoma treated with nivolumab." (PMID 31080803, 2019). "Characteristics and serum levels of CXCL5, CXCL10, and CCL22 in patients with cutaneous melanoma." (PMID 31080803, 2019).
depression (4 papers, 2018 to 2023). "Among their top 10 most significant proteins that were altered after treatment were the same proteins that we found in our OPLS and OPLS-DA models for depression and anxiety (CXCL6, STAMPB, CXCL1, SIRT2, AXIN1, CXCL5, ST1A1, and IL-7)." (PMID 36979692, 2023). "Lower peripheral levels of CXCL5 (RANTES) was observed in people with psychiatric disorders such as schizophrenia and recurrent depressive disorder with suicidal ideation." (PMID 30096932, 2018).
gout (4 papers, 2022 to 2025). A condition characterized by painful swelling of the joints, which is caused by deposition of urate crystals. "A recent study has evaluated the involvement of CXCL5 for pain, showing how serum levels of this marker are upregulated in male patients with gouty arthritis." (PMID 41020650, 2025). "The percentage of CXCL5-responding neurons was significantly increased in the gout model group vs. the control group." (PMID 38627393, 2024). "We confirmed CXCR2 expression in human dorsal root ganglion neurons and CXCL5 level upregulation in serum from male patients with gouty arthritis." (PMID 38627393, 2024). "Here we show that CXCL5 activates CXCR2 expressed on nociceptive sensory neurons to drive gout pain and inflammation." (PMID 38627393, 2024). "Here, the authors demonstrate that CXCL5 expression is increased in ankle joints of gouty arthritis model mice." (PMID 38627393, 2024). "Our study demonstrates CXCL5-neuronal CXCR2-TRPA1 axis contributes to gouty arthritis pain, neutrophil influx and inflammation that expands our knowledge of immunomodulation capability of nociceptive sensory neurons." (PMID 38627393, 2024). "CXCL5 neutralizing antibody significantly reduced neutrophil and macrophage infiltrations in ankle joints of gout model mice, indicated by immunostaining and myeloperoxidase (MPO) assay." (PMID 38627393, 2024). "Immunostaining of ankle joint from gout model mice showed that a majority (56.6%) of CXCL5+ cells co-stained with fibroblast cell marker vimentin and to a lesser extent, co-stained with markers for macrophage (Iba-1) and mast cell (avidin) (30.0% and 12.3%, respectively)." (PMID 38627393, 2024). "Regarding the relatively high expression of CXCL5 in the inflamed ankle joints and its high potency in exciting sensory neurons, neutralization of CXCL5 can produce the most effective ameliorating effect on both pain and inflammation in gout model mice." (PMID 38627393, 2024). "We hypothesize that increased CXCL5 in ankle joints of gout model mice might act upon its receptors expressed on peripheral sensory neurons to produce pain." (PMID 38627393, 2024). "Synovial fluids from patients with RA and gout elicit CXCL1 and CXCL5 from synovial fibroblasts via IRAK1." (PMID 35801586, 2022). "We then studied CXCL5-induced Ca2+ responses in DRG neurons from control and gout model mice." (PMID 38627393, 2024). "Indeed, synovial fluid from multiple patients with RA or gout elicited CXCL1 and CXCL5 release from murine synovial fibroblasts." (PMID 35801586, 2022).
Granuloma (4 papers, 2011 to 2026). A compact, organized collection of mature mononuclear phagocytes, which may be but is not necessarily accompanied by accessory features such as necrosis. "MMP1+CXCL5+ fibroblast, however, showed the largest difference for marker expression between the Visium spots on the granuloma cuff and those inside/outside the cuff." (PMID 41489684, 2026). "We also observed a significant increase in the imputed frequency of MMP1+CXCL5+ fibroblasts in TB LN granuloma compared with control LNs via deconvolution of bulk RNA-seq profiles." (PMID 41489684, 2026). "In particular, the MMP1+CXCL5+ fibroblast subset, expressing a myofibroblast-like gene signature, was associated with severe disease and higher bacterial burden in nonhuman primate granulomas." (PMID 41489684, 2026).
ischemia (4 papers, 2023 to 2024). A hypoperfusion of the BLOOD through an organ or tissue caused by a PATHOLOGIC CONSTRICTION or obstruction of its BLOOD VESSELS, or an absence of BLOOD CIRCULATION. "After hindlimb ischemia surgery, the blood flow was repaired by treatment with CXCL5 neutralizing antibody compared to the DM group." (PMID 37420254, 2023). "Meanwhile, CXCL5 inhibition repaired ischemia tissue angiogenesis with upregulated VEGF and SDF-1 in both mouse models of type 1 and type 2 DM in vivo." (PMID 37420254, 2023). "Second, systemic CXCL5 suppression improved the blood flow recovery after hindlimb ischemia surgery, increased the number of EPCs in circulation, and upregulated VEGF and SDF-1 expressions in the ischemic gastrocnemius muscle in DM mice." (PMID 37420254, 2023). "The authors constructed an ischemic/hypoxic model in human brain microvascular endothelial cells (BMECs) and investigated the function of CXCL5 and its potential value as a therapeutic target for ischemia-induced brain disease." (PMID 36982232, 2023). "Consequently, the decreased release of CXCL5 in the I/R+Ruxo group of this project suggests that ruxolitinib protects the vascular endothelium from ischemia." (PMID 37511486, 2023).
malaria (4 papers, 2021 to 2023). Malaria is a serious and sometimes fatal disease caused by a parasite that commonly infects a certain type of mosquito which feeds on humans. "Distinct cytokine profiles in malaria and filariasis coinfections were IL-1Ra, IL-10, CXCL5, CXCL8, and CXCL10." (PMID 36716305, 2023). "They demonstrated that malaria and L. loa co-infections had decreased levels of C-X-C motif chemokine 5 (CXCL5) and comparable levels of CX3CL1, CXCL7, CXCL9, CXCL11, and CCL28 compared with malaria monoinfection." (PMID 36269701, 2022). "Our studies showed that co-incubation of brain ECs with plasma from malaria patients resulted in significantly increased secretion of IL-11, CXCL5, CXCL10, VEGF and angiopoietin-like protein 4 (ANGPTL4)." (PMID 34359826, 2021). "Stimulation of ECs with plasma from malaria patients resulted in significantly increased levels of IL-11, CXCL5, CXCL8, CXCL10 and VEGF in comparison to stimulation of ECs using plasma from healthy controls." (PMID 34359826, 2021). "In addition, significant decreases in IL-10 and CXCL5 levels were observed in coinfections compared to malaria monoinfections." (PMID 36716305, 2023). "Interestingly, the concentration of CXCL5 in the plasma of malaria patients was below the detected levels in controls." (PMID 34359826, 2021). "Interestingly, CXCL5 is the only chemokine that was detected at significantly lower levels in plasma of malaria patients than in plasma of healthy controls." (PMID 34359826, 2021). "Culturing ECs with plasma from malaria patients (27 returning travellers) resulted in significantly increased secretion of IL-11, CXCL5, CXCL8, CXCL10, vascular endothelial growth factor (VEGF) and angiopoietin-like protein 4 (ANGPTL4) if compared to matching controls (22 healthy individuals)." (PMID 34359826, 2021). "An inverted ratio in cytokine concentration between the malaria and control group in plasma and supernatant, as observed in CXCL5 and ANGPTL4, does not constitute a contradiction." (PMID 34359826, 2021). "The reason for the lower amount of CXCL5 in plasma of malaria patients is not yet clear." (PMID 34359826, 2021).
rectum adenocarcinoma (4 papers, 2020 to 2024). An adenocarcinoma arising from the rectum. "In rectum adenocarcinoma, CXCL1 and CXCL3 negatively correlated with EMT, while CXCL5, CXCL6, PPBP, and CXCL8 were positively correlated." (PMID 37686093, 2023).
Trichiasis (4 papers, 2012 to 2019). Inversion and rubbing of the eyelashes against the globe of the eye. "This identified a variety of pro-inflammatory (IL1B, TNFA, S100A7, CXCL5, NOS2A) and tissue remodelling factors (MMP7, MMP9 and MMP12), which were associated with conjunctival scarring and trichiasis before surgery." (PMID 23285311, 2012). "Previous studies have shown that a number of innate epithelial pro-inflammatory mediators (IL1B, S100A7, CXCL5), matrix factors (SPARCL1, CTGF, collagens) and matrix metalloproteinases (MMPs 7, 9, 12) are associated with progressive trachomatous scarring, trichiasis and post-operative trichiasis." (PMID 37426632, 2019). "The upregulation of pro-inflammatory mediators and cell markers (CCL2, CCL3, CXCL5,IL1B, IL6, CHUK, FUT4 andPTPRC) is indicative of higher levels of inflammation and leukocyte infiltration in the conjunctival tissue of patients who developed ECA following trichiasis surgery." (PMID 37426632, 2019).
Autoimmunity (3 papers, 2015 to 2023). The occurrence of an immune reaction against the organism's own cells or tissues. "We showed that CXCR1 strengthened the pro-inflammation cytokines production of DCs and further accelerated inflammation and autoimmunity disease progression via a positive feedback loop of CXCL5/CXCR1/HIF-1α." (PMID 37709757, 2023).
Cachexia (3 papers, 2024 to 2025). Severe weight loss, wasting of muscle, loss of appetite, and general debility related to a chronic disease. "Thus, elevated CXCL5 levels in patients may be associated with increased weight loss and/or a more rapid progression of cachexia, especially if CXCL5 is upregulated in the tumor stromal compartment." (PMID 41392310, 2025). "Further stratification by cachexia status for ENA-78/CXCL5, GRO-α /CXCL1 and GDF-15 (as a comparison) shows that ENA-78/CXCL5 and GRO-α/CXCL1 levels were unchanged for any R&E group when stratified by cachexia status." (PMID 39989973, 2025). "When we performed a linear model with either ENA-78/CXCL5 or GRO-α as response variables and R&E, cachexia status, stage, sex, and BMI as predictor variables, NHB demonstrated significantly increased ENA-78/CXCL5 and GRO-α/CXCL1 compared to other R&E groups." (PMID 39989973, 2025). "CXCL5 and H3Cit were not reliable biomarkers for cancer cachexia, nor significantly related to QoL, appetite or cachexia." (PMID 38744744, 2024).
chorioamnionitis (3 papers, 2012 to 2025). A morphologic finding indicating inflammation of the fetal sac membranes. "High CXCL5 levels were observed in clinical chorioamnionitis of preterm births and in surgically resected tissue samples of necrotizing enterocolitis from preterm infants." (PMID 26738635, 2016).
congestive heart failure (3 papers, 2008 to 2018). Failure of the heart to pump a sufficient amount of blood to meet the needs of the body tissues, resulting in tissue congestion and edema. "Damås and colleagues showed that circulating levels of CXCL8, CXCL1 (GRO-α), and CXCL5 (ENA-78) gradually increased in patients with congestive heart failure (CHF) in parallel with an increase in NYHA functional class." (PMID 27242392, 2016).
emphysema (3 papers, 2011 to 2019). "Although the mechanism of RXR partial agonists in the progression of emphysema are not fully elucidated, NEt-4IB may play a critical role in controlling the accumulation and activation of neutrophils by suppressing IL-17, KC and CXCL5 and by regulating the activation of Th1 cells." (PMID 30606200, 2019).
encephalitis (3 papers, 2018 to 2025). An acute inflammatory process affecting the brain parenchyma. "Significantly higher levels of CCL11 (p = 0.0107), CCL2 (p = 0.0182), CCL5 (p = 0.0171) and CXCL5 (p = 0.0049) were observed in encephalitis patients." (PMID 40517242, 2025). "In vitro, human brain microvasculature endothelial cells secrete CXCL1 and CXCL5 and favor transmigration of neutrophils under IL-22 stimulation, confirming that findings from animal experiments may apply to human encephalitis." (PMID 29678185, 2018). "Additionally, marked elevation of several immune markers (CCL11, CCL2, CCL5, CXCL5, and IL-12p70) in the CSF of encephalitis patients may explain the more severe course of infection and poorer outcomes observed (highest number of neurological symptoms and ICU admissions)." (PMID 40517242, 2025). "CXCL5 is unique in that it further enhances infiltration of neutrophils during CNS infections with HIV-1 and West Nile virus, leading to viral-induced encephalitis and related CNS pathologies." (PMID 32225060, 2020).
endometritis (3 papers, 2010 to 2021). An acute or chronic, usually bacterial infectious process affecting the endometrium. "Several studies have found that the mRNAs of interleukin (IL) 1A, IL1B, IL6, IL8, chemokine CXL ligand (CXCL) 3, and CXCL5 are up-regulated in dairy cows with endometritis." (PMID 33718475, 2021). "Previous studies show that mRNA of proinflammatory cytokines interleukin-1 alpha (IL1A), IL1B, IL6, and TNF and expression of chemokines IL8 and CXCL5 increased in endometrial epithelial cells during the estrous cycle and subclinical or clinical endometritis." (PMID 33324700, 2020). "Real-time RT-PCR has revealed that CXCL5, IL1B, IL8 and TNF mRNA are significantly higher expressed in the endometrium of cows with subclinical or clinical endometritis than in healthy cows." (PMID 21176181, 2010). "Recently, it was suggested that CXCL5, IL1B, IL8 and TNF may be suitable markers for the detection of subclinical endometritis because mRNA levels were elevated compared with samples from healthy cows." (PMID 21176181, 2010).
gastric tumor (3 papers, 2010 to 2023). "Gene ontology analysis of gene expression in the gastric tumors indicates that PPARδ, MMP12, MMP13, Cxcl1, Cxcl5, S100A8, and S100A9 share both common and disparate pathway interactions that likely contributed to the tumorigenic phenotype." (PMID 21318167, 2010).
Hyperglycemia (3 papers, 2016 to 2021). An increased concentration of glucose in the blood. "Five C-X-C chemokines (CXCL 1- CXCL5) were also upregulated in hyperglycemia." (PMID 31415598, 2019).
hyperlipidemia (3 papers, 2011 to 2025). "Based on baseline characteristics of the GSE90074 dataset, four parameters significantly associated with disease status were identified: gender, hyperlipidemia, disease severity (CAD_class), and the inflammatory marker CXCL5." (PMID 41583468, 2025).
Hypertension (3 papers, 2011 to 2021). The presence of chronic increased pressure in the systemic arterial system. "Our findings, along with existing data, support the need for future investigation of CXCL5 as a hypertension- and CVD-susceptibility gene." (PMID 23245743, 2012). "The role of CXCL5 as a hypertension- and CVD-susceptibility gene should be further explored." (PMID 23245743, 2012). "Monocyte recruitment is the key factor in the development of vascular inflammation, followed by adhesion molecules (VCAM-1 and ICAM-1), inflammatory factors (TNF-α and IL-6), and chemokines (CCL2, CXCL5, CXCL8, and CXCL10) released during hypertension." (PMID 34335249, 2021).
Infertility (3 papers, 2018 to 2025). "The mean concentration of CXCL5 in fertile men was reported to be 248 pg/mL, with higher concentrations in the SP of men with varicocoele‐induced infertility." (PMID 36891953, 2023). "We also found the neutrophil activating peptide C-X-C motif chemokine 5 (CXCL5) to be significantly higher in the infertile heifers (P = 0.04, 1.53 ± 0.27 fold), when compared to the fertile heifers (1.04 ± 0.07 fold)." (PMID 30181662, 2018). "Furthermore, infertile heifers had significantly higher expression of TNFα, IL-6, and CXCL5 in their white blood cells." (PMID 30181662, 2018). "MR results revealed genetic correlations between abnormal ADA, artemin, OSM, caspase 8, CXCL5, interleukin‐18, and LIFR levels and infertility." (PMID 40525280, 2025).